LIMK1 (LIM domain kinase 1)
Diseases named in the same sentence as LIMK1 in open-access papers (continued):
Sharing a sentence is not in itself a finding about the gene and the disease.
lymph node metastasis (7 papers, 2016 to 2023). "The multivariate logistic regression analysis demonstrated that LIMK1 was independent risk factor for PCa lymph node metastasis (P < .001)." (PMID 32168432, 2020). "Multivariate logistic regression analysis demonstrated that LIMK1 was an independent risk factor for PCa lymph node metastasis (P < .05)." (PMID 32168432, 2020). "Up‐regulation of LIMK1 was associated with prostate volume, prostate‐specific antigen, prostate‐specific antigen density, Gleason score, T stage, lymph node metastases, extracapsular extension and seminal vesicle invasion, and positive surgical margin." (PMID 32168432, 2020). "Overexpression of LIMK1 has been reported to be associated with higher tumor metastasis stage and lymph node metastasis." (PMID 28440035, 2017). "Finally, in the multivariate analysis, an elevated LIMK1 level was an independent risk factor for lymph node metastasis and biochemical recurrence after prostatectomy." (PMID 37371647, 2023). "Increased LIMK1 mRNA expression was associated with lymph node metastases and high TNM stage." (PMID 34149814, 2021). "Moreover, the multivariate logistic regression analysis demonstrated that LIMK1 was independent risk factor for PCa lymph node metastasis." (PMID 32168432, 2020). "Higher expression levels of LIMK1 were observed in male patients (P = 0.004), patients with lymph node metastases (P = 0.022), and patients with high TNM stage (P = 0.048)." (PMID 34149814, 2021). "The upregulated mRNA expression of LIMK1 is positively correlated with lymph node metastases and high TNM stage." (PMID 34149814, 2021). "The results demonstrated that lymph node metastases were significantly associated with the preoperative PSA level, postoperative Gleason score, extracapsular extension, seminal vesicle invasion, positive surgical margin and the LIMK1 expression (P < .05)." (PMID 32168432, 2020). "Subgroup analysis stratified by the lymph node metastasis demonstrated that lymph node metastases were significantly associated with the preoperative PSA level, postoperative Gleason score, extracapsular extension, seminal vesicle invasion, positive surgical margin and the LIMK1 expression." (PMID 32168432, 2020). "Moreover, since lymph node metastases and high TNM stage are correlated with poor survival, we speculated that the upregulation of LIMK1 is a biomarker of poor prognosis." (PMID 34149814, 2021).
ovarian carcinoma (6 papers, 2015 to 2021). A malignant neoplasm originating from the surface ovarian epithelium. "The LIMK1/cofilin/F-actin signaling axis has been reported to promote cell invasion in ovarian cancer and non-small cell lung carcinomas." (PMID 34079084, 2021).
fragile X syndrome (5 papers, 2016 to 2026). A genetic syndrome caused by mutations in the FMR1 gene which is responsible for the expression of the fragile X mental retardation 1 protein. "We hope thatthe developed tool compounds will help to further elucidate the detailedroles of LIMK1-specific signaling and may serve as a starting pointfor the treatment of Fragile X syndrome, in which LIMK1 activity isselectively upregulated." (PMID 40598933, 2025).
glioblastoma (5 papers, 2018 to 2025). The most malignant astrocytic tumor (WHO grade IV). "To further elucidate the role of phosphocofilin in glioblastoma cells we applied inhibitors for ROCK1/2 and LIMK1/2 to our model." (PMID 29724193, 2018). "An interaction between endogenous PKCζ and LIMK1, but not LIMK2, was shown in the LN229 glioblastoma cell line upon EGF stimulation." (PMID 36899941, 2023).
Intellectual disability (5 papers, 2011 to 2021). "Mice with mutations in PAK, WAVE-1, or LIMK-1 have learning and memory defects while mutations in human genes encoding regulators (ARHGEF6, OPHN1) or effectors (LIMK-1, PAK3) are associated with mental retardation." (PMID 21387015, 2011). "Protein kinases such as Pak3, Limk1, ERK, and RSK2 have been implicated in intellectual disability." (PMID 35011609, 2021).
lung adenocarcinoma (5 papers, 2015 to 2022). A carcinoma that arises from the lung and is characterized by the presence of malignant glandular epithelial cells. "To evaluate the association between the mRNA expression of LIMK1 and clinical pathological characteristics of lung adenocarcinoma samples, we performed Mann-Whitney U-test and logistic regression analysis." (PMID 34149814, 2021). "In light of Kaplan-Meier curves and univariate analysis, we confirmed that high mRNA expression of LIMK1 is associated with short OS and LIMK1 can be used as a potential biomarker of poor prognosis for lung adenocarcinoma." (PMID 34149814, 2021). "On the basis of our finding, we conclude that LIMK1 might act as a potential diagnostic biomarker to differentiate lung adenocarcinoma from normal controls." (PMID 34149814, 2021). "Furthermore, in light of Kaplan-Meier curves and log-rank test, lung adenocarcinoma patients with high mRNA expression of LIMK1 are associated with a decreased survival rate than those with low LIMK1 levels." (PMID 34149814, 2021). "ROC curve analysis indicated that LIMK1 could be a promising diagnostic biomarker to differentiate lung adenocarcinoma from normal tissues." (PMID 34149814, 2021). "MTT assay demonstrated that the IC50 value of DDP was decreased after transfected with si-circ-LIMK1#1 in A549/DDP and H1975/DDP cells, indicating that circ-LIMK1 knockdown enhanced DDP sensitivity in DDP-resistant lung adenocarcinoma cells." (PMID 36304135, 2022). "This study aimed to unveil the detailed role and new mechanism of circ-LIMK1 in lung adenocarcinoma." (PMID 36304135, 2022). "The expression of circ-LIMK1 had been detected in our experiments, then the specific role of circ-LIMK1 in DDP-resistant lung adenocarcinoma cells needs to be further explored." (PMID 36304135, 2022). "Meanwhile, it was found that circ-LIMK1 was significantly correlated with the stage of lung adenocarcinoma patients and other clinical characteristics such as DDP resistance." (PMID 36304135, 2022). "Our study had confirmed the regulatory effect of circ-LIMK1 on lung adenocarcinoma cells at the cellular level, and we would further verify the effect of circ-LIMK1 in vivo." (PMID 36304135, 2022). "Collectively, circ-LIMK1 regulated DDP resistance in lung adenocarcinoma by targeting miR-512-5p/HMGA1 axis." (PMID 36304135, 2022). "In our study, circ-LIMK1 was highly expressed in DDP-resistant lung adenocarcinoma specimens and cells." (PMID 36304135, 2022). "The ROC curve analysis showed that with a cutoff level of 4.908, the accuracy, sensitivity, and specificity for LIMK1 differentiate lung adenocarcinoma from adjacent controls were 69.5, 93.2, and 71.9%, respectively." (PMID 34149814, 2021). "In conclusion, in this study, we showed for the first time that mRNA expression of LIMK1 is upregulated in lung adenocarcinoma and positively correlated with lymph node metastases and high TNM stage." (PMID 34149814, 2021). "Upregulated LIMK1 is significantly correlated with poor survival and immune infiltrates in lung adenocarcinoma." (PMID 34149814, 2021). "Paired data analysis showed that the mRNA expression levels of LIMK1 in lung adenocarcinoma tissues (n = 57) were significantly higher than those in adjacent normal tissues (n = 57) (5.584 ± 0.747 vs. 4.320 ± 0.442, P < 0.001)." (PMID 34149814, 2021). "In this study, we found that the mRNA expression of LIMK1 is upregulated in lung adenocarcinoma tissues." (PMID 34149814, 2021). "We further evaluated the diagnostic and prognostic values, the correlation with immune infiltrates of LIMK1 for lung adenocarcinoma." (PMID 34149814, 2021). "Immunohistochemical staining from HPA also revealed LIMK1 protein was upregulated in lung adenocarcinoma tissue." (PMID 34149814, 2021). "On the basis of our data, we concluded that LIMK1 can be used as a biomarker of poor prognosis for determining prognosis in lung adenocarcinoma." (PMID 34149814, 2021).
lung adenocarcinoma (continued). "The prognostic values and correlation with immune infiltrates of LIMK1 in lung adenocarcinoma are still not fully understood." (PMID 34149814, 2021). "To investigate the value for LIMK1 to distinguish lung adenocarcinoma samples from normal smples, we performed a ROC curve analysis." (PMID 34149814, 2021). "Our study suggests that LIMK1 can be used as a biomarker of poor prognosis and potential immune therapy target in lung adenocarcinoma." (PMID 34149814, 2021). "PrognoScan result with two different datasets also indicated that high expression of LIMK1 was correlated with poor overall survival in lung adenocarcinoma." (PMID 34149814, 2021). "The expression of LIMK1 in lung adenocarcinoma tissues was significantly upregulated than those in adjacent normal tissues." (PMID 34149814, 2021). "Second, to further examine the detailed mechanism of the impact of LIMK1 on immune infiltration in lung adenocarcinoma, in vivo/vitro experiments should be designed." (PMID 34149814, 2021). "Our results showed that LIMK1 had a significantly high AUC value in the detection of lung adenocarcinoma, with 69.5% in sensitivity, 93.2% in specificity, and 71.9% in accuracy." (PMID 34149814, 2021). "Unpaired data analyses also showed that the mRNA expression levels of LIMK1 in lung adenocarcinoma tissues (n = 535) were significantly higher than those in adjacent normal tissues (n = 59) (5.314 ± 0.847 vs. 4.324 ± 0.437, Mann-Whitney U-test, P < 0.001)." (PMID 34149814, 2021). "Transcriptional expression profiles of LIMK1 between lung adenocarcinoma tissues and normal tissues were downloaded from the Cancer Genome Atlas (TCGA)." (PMID 34149814, 2021). "The OS of lung adenocarcinoma patients with high-level of LIMK1 was significantly shorter than those with low-level of LIMK1 (43.1 vs. 55.1 months, P = 0.028)." (PMID 34149814, 2021). "The result showed that the protein expression of LIMK1 in lung adenocarcinoma was significantly higher than those in normal tissues." (PMID 34149814, 2021). "In order to validate the clinical value of LIMK1 in the diagnosis of lung adenocarcinoma, we conducted ROC curve analysis." (PMID 34149814, 2021). "Kaplan-Meier survival analysis showed lung adenocarcinoma patients with high- LIMK1 had a worse prognosis than those with low- LIMK1 (43.1 vs. 55.1 months, P = 0.028)." (PMID 34149814, 2021). "MiR-512-5p absence could restore the repressive effects of circ-LIMK1 knockdown on lung adenocarcinoma cell phenotypes." (PMID 36304135, 2022). "The construction of mouse transplantation model confirmed that circ-LIMK1 could regulate DDP resistance in lung adenocarcinoma in vivo." (PMID 36304135, 2022). "Therefore, we evaluated the prognostic role of LIMK1 and its correlation with immune infiltrates in lung adenocarcinoma." (PMID 34149814, 2021). "Our research suggests that LIMK1 could be regarded as a potential biomarker of poor prognosis to identify lung adenocarcinoma patients with poor clinical outcomes and may play a specific role in immune infiltration." (PMID 34149814, 2021). "Given the condition that mRNA expression of LIMK1 is significantly higher in lung adenocarcinoma than in normal lung tissues, we speculate LIMK1 can act as a biomarker to differentiate lung adenocarcinoma from normal controls." (PMID 34149814, 2021). "Our study links the overexpression of LIMK1 and poor survival in lung adenocarcinoma." (PMID 34149814, 2021). "To test this hypothesis, we evaluated the prognostic role of LIMK1 in lung adenocarcinoma based on data from The Cancer Genome Atlas (TCGA)." (PMID 34149814, 2021). "We also confirmed that LIMK1 is significantly upregulated in lung adenocarcinoma." (PMID 34149814, 2021). "In this study, we found that LIMK1 is upregulated in lung adenocarcinoma." (PMID 34149814, 2021). "It has been reported that circ-LIMK1 (circ_0001715) might be a biomarker in lung adenocarcinoma." (PMID 36304135, 2022).
lung adenocarcinoma (continued). "Therefore, we continued to explore whether circ-LIMK1 could regulate DDP resistance process of lung adenocarcinoma through targeting miR-512-5p." (PMID 36304135, 2022). "In summary, we preliminarily confirmed that circ-LIMK1 could regulate the development of lung adenocarcinoma and DDP chemoresistance, and on this basis, we speculated that circ-LIMK1 might be a potential target for the diagnosis and prognosis of lung adenocarcinoma." (PMID 36304135, 2022). "In our study, the targeting relationship between miR-512-5p and circ-LIMK1 or HMGA1 and their functions in the progression of lung adenocarcinoma were confirmed, which provided new ideas for overcoming DDP resistance in lung adenocarcinoma in the future." (PMID 36304135, 2022). "In a word, the expression of circ-LIMK1 was at a higher level in DDP-resistant tissues and in cells of lung adenocarcinoma." (PMID 36304135, 2022). "Acting as an oncogenic driver, circ-LIMK1 can regulate DDP resistance and tumor development in lung adenocarcinoma by targeting miR-512-5p/HMGA1 pathway." (PMID 36304135, 2022). "In summary, all the findings confirmed the relationships among circ-LIMK1, miR-512-5p, and HMGA1, as well as their functional mechanism in DDP-resistant lung adenocarcinoma." (PMID 36304135, 2022). "Moreover, LIMK1 may play a specific role in immune infiltration in lung adenocarcinoma." (PMID 34149814, 2021). "Circ-LIMK1 could regulate the expression of HMGA1 by targeting miR-512-5p and thus regulate the related processes of DDP-resistant lung adenocarcinoma cells and promote sensitivity of DDP-resistant lung adenocarcinoma cells." (PMID 36304135, 2022). "Taken together, these results suggested that LIMK1 is correlated with lymph node metastases and high TNM stage, further suggesting LIMK1 may act as a biomarker of poor prognosis for lung adenocarcinoma." (PMID 34149814, 2021). "Given the upregulation of LIMK1 is positively correlated with lymph node metastases and high TNM stage, we speculated LIMK1 is involved in the development of lung adenocarcinoma." (PMID 34149814, 2021). "The expression level of circ-LIMK1 was higher in A549/DDP and H1975/DDP cells in comparison to their parental cells, which proved that circ-LIMK1 might be involved in DDP resistance of lung adenocarcinoma." (PMID 36304135, 2022). "However, the prognostic values of LIMK1 and correlation with immune infiltrates in lung adenocarcinoma are still not understood." (PMID 34149814, 2021). "However, the expression of LIMK1 and its prognostic value has not been fully investigated in lung adenocarcinoma." (PMID 34149814, 2021). "However, the prognostic value of LIMK1 has not been investigated in lung adenocarcinoma." (PMID 34149814, 2021). "However, the targeting relationship between miR-512-5p and circ-LIMK1 and its role on DDP resistance in lung adenocarcinoma are not clear." (PMID 36304135, 2022).
schizophrenia (5 papers, 2017 to 2023). A major psychotic disorder characterized by abnormalities in the perception or expression of reality. "In addition, NRG1, whose gene mutations are linked with increased susceptibility to schizophrenia, affects dendritic spines and synaptic function through interacting and regulating LIMK1 signaling." (PMID 34440848, 2021). "Treatment with the LIM kinase inhibitor Pyr1 rescued these behavioural impairments, making LIMK1 a potential target for the treatment of schizophrenia." (PMID 36899941, 2023). "In patients with schizophrenia, the expression of LIMK1 was dysregulated, which makes LIMK1 a potential target for therapeutic interventions." (PMID 34440848, 2021). "Whether manipulations of LIMK1 signaling pathway have an effect in other animal models of schizophrenia remains to be examined." (PMID 34440848, 2021). "An analysis of CDC42-related gene expression displayed increased mRNA levels of LIMK1 and LIMK2 in the DLPFC of subjects with schizophrenia, implying that the CDC42/PAK/LIMK pathway has a role in the spine deficits in the DLPFC of SZ subjects." (PMID 36899941, 2023). "For example, through pharmacological inhibition of LIMK1 using Pyr1, it was shown that the synaptic and behavioural deficits, including reduced spine density, impaired LTP, social withdrawal and anxiety-like behaviour in MAP6 KO mice (an animal model of schizophrenia), were rescued." (PMID 34440848, 2021).
thyroid cancer (5 papers, 2014 to 2022). "LATS1 binds to LIM kinase (LIMK) 1 and inhibits the activity of LIMK1 to regulate cytokinesis, and LIMK1 was implicated in the pathogenesis of thyroid cancer and ATC." (PMID 35350839, 2022). "We found that LIMK1 protein expression in thyroid cancer cell lines (C643, XTC-1, FTC-133, and TPC-1) was decreased with miR-20a overexpression." (PMID 24858712, 2014). "We found that LIMK1 was a target of miR-20a in thyroid cancer cell lines and direct knockdown of LIMK1 recapitulated the effect of miR-20a in thyroid cancer cells." (PMID 24858712, 2014). "It acts as a tumor suppressor in thyroid cancer cells and targets LIMK1." (PMID 27916938, 2016). "We also found that miR-20a regulates LIMK1 expression, suggesting that LIMK1 is a target gene that may mediate the suppressive effects of miR-20a on growth and invasion of thyroid cancer cells." (PMID 24858712, 2014). "Lastly, we show that LIMK1 recapitulates the effects of miR-20a in thyroid cancer cells." (PMID 24858712, 2014). "Based on the results from our genome-wide gene expression and target prediction analyses, we asked whether miR-20a overexpression affects LIMK1 expression in thyroid cancer cell lines." (PMID 24858712, 2014). "We found that miR-20a regulates LIMK1 expression in thyroid cancer cell lines." (PMID 24858712, 2014). "In this study, LIMK1 is also verified as a direct target gene of miR-93, which is also in accord with that LIMK1 is a target gene of miR-20a that may mediate the suppressive effects on growth and invasion of thyroid cancer cells." (PMID 31541994, 2019). "Given that miR-20a overexpression downregulated LIMK1 in thyroid cancer cell lines and the most prominent effect of miR-20a on thyroid cancer cells was the inhibition of cellular invasion, we explored whether LIMK1 has an effect on cellular invasion and migration." (PMID 24858712, 2014).
Anxiety (4 papers, 2021 to 2025). Intense feelings of nervousness, tension, or panic often arise in response to interpersonal stresses. "In contrast, expression of LIMK1-EGFP in APP/PS1 mice significantly improved social recognition memory in both three-chamber and five-trial repeated exposure tests, without affecting locomotor activity or anxiety-like behavior." (PMID 34315506, 2021).
autism (4 papers, 2017 to 2023). Persistent deficits in social interaction and communication and interaction as well as a markedly restricted repertoire of activity and interest as well as repetitive patterns of behavior. "PAK2 haplo-insufficiency has also been reported in ASD patients and PAK2 heterozygous mice exhibited a marked decrease in synapse density and impaired LTP, as well as autism-relevant behaviours that were related to reduced activity of LIMK1 and subsequent activation of cofilin." (PMID 34440848, 2021).